ERBB2 (erb-b2 receptor tyrosine kinase 2)
Diseases named in the same sentence as ERBB2 in open-access papers (continued):
Sharing a sentence is not in itself a finding about the gene and the disease.
breast cancer (continued). "Conversely, the 18-kDa LOX propeptide was found to be an effective inhibitor of the more invasive phenotype of breast cancer cells driven by ERBB2 and has been suggested to improve treatment in this subtype of breast cancer." (PMID 21731642, 2011). "There is also growing awareness of the importance of the erbB2/erbB3 heterodimer in breast cancer progression." (PMID 21939528, 2011). "IBC is an aggressive clinical subtype of breast cancer that is an extremely invasive and metastatic disease that falls into two major subtypes; Basal-like or ErbB2 overexpressing." (PMID 21505458, 2011). "To summarize, we validated in this study that the expression of NEDD9 was frequently upregulated in highly aggressive TNBC breast cancer cell lines as well as in aggressive breast tumors, including ERBB2-positive and triple-negative subtypes." (PMID 21829474, 2011). "Amplification of the ERBB2 oncogene is considered an important tumor driver, and has been reported in approximately 25% of breast cancers." (PMID 21731642, 2011). "Women with breast cancer that overexpresses HER2/erbB2 account for 15–30% of all diagnosed pathology subtypes and are usually associated with an unfavorable clinical outcome." (PMID 21988766, 2011). "We also studied if the combination therapy of lapatinib plus GSI can induce tumour regression of ErbB-2-positive breast cancer." (PMID 21847123, 2011). "We used several cell lines in our in vitro studies; however, we chose to use BT474 ErbB-2-positive breast cancer cells as they are sensitive to trastuzumab and have been used numerous times in preclinical studies to represent the clinical setting." (PMID 21847123, 2011). "Trastuzumab-resistant, ErbB-2-positive BT474 breast cancer cells were generated by treating cells with 10 μg ml−1 trastuzumab for 6 months in vitro." (PMID 21847123, 2011). "In rat ErbB2 tolerant mice, the RRT plasmid is efficacious against both rat ErbB2+ transplantable and autochthonous mammary tumors, but is devoid of any significant effect against human ErbB2+ transplantable tumors." (PMID 24212954, 2011). "The purpose of this study was to assess the ability of circulating IGF-I to independently initiate mammary tumorigenesis and/or accelerate the progression of ErbB2 mediated mammary tumor growth." (PMID 21867536, 2011). "In fact, the prevalence of ErbB2 overexpression in invasive and metastatic breast cancer is only half that of early stage cancers, which has been a perplexing phenomenon." (PMID 21647371, 2011). "The discovery that erbB2 (also called Her2 or neu) plays a critical role in some types of human breast cancer rapidly led to strategies aimed at interrupting the signaling function of this receptor." (PMID 22758623, 2011). "The second report did not discriminate between the intrinsic and the immunological contribution of STAT1-deficiency but came nevertheless to the conclusion that Stat1−/− × ERBB2/neu mice develop mammary tumors significantly faster than control mice." (PMID 22185785, 2011). "Stat3 knockdown in murine models of ErbB2-mediated breast carcinoma altered epithelial adhesion and polarity." (PMID 22140473, 2011). "In rat ErbB2 tolerant mice the immunity induced by RHuT confers full protection against a challenge of tumor cells expressing rat ErbB2, and is also the most effective against the onset of mammary carcinomas driven by the expression of rat ErbB2." (PMID 24212954, 2011). "As in breast carcinomas, amplification of ERBB2 is found in 20-30% of adenocarcinomas of the esophagus, gastroesophageal junction and stomach, and is associated with poorer survival." (PMID 22014070, 2011).
breast cancer (continued). "In several studies, CRIP1 has been proposed as a novel biomarker for breast cancer and its precursor lesions which can be triggered by ERBB2 overexpression." (PMID 22202598, 2011). "As gastric cancer reveals more heterogeneity in the expression of erbB2 than breast cancer, a modified scoring system for gastric cancer was agreed upon at an international consensus meeting, and used by the panel of pathologists in the ToGA study." (PMID 22014070, 2011). "This supports the growing evidence suggesting a possible advantage of using IGF-IR and ErbB2-directed therapies concurrently in the treatment of breast cancer." (PMID 20825649, 2010). "To gain insight into the prevalence and assessment of ErbB2-positive breast cancer in Asia through a literature survey, we formed the Early Breast Cancer Working Group (EBCWG)." (PMID 20715159, 2010). "Nevertheless, our survey, based on data from 14,398 patients in 7 Asian countries, indicates that the reported prevalence of ErbB2-positive breast cancer has varied widely from 6% to 65%." (PMID 20715159, 2010). "Genes of known importance in breast cancer and estrogen signaling, including ERBB2, PGR, MYC, CLU, and NCOA2, were among those identified as Sin3A-responsive." (PMID 20920219, 2010). "Recently, ErbB2 was shown to induce Notch1 activity in breast cancer cells, which is consistent with its ability to drive mammary stem cell proliferation, tumorigenesis and invasion." (PMID 20727204, 2010). "The objectives of our literature survey were to summarize the reported prevalence of ErbB2-positive breast cancer in 7 Asian countries and to examine the ErbB2 assessment methods used in these countries." (PMID 20715159, 2010). "Taken together, these results provide a strong preclinical evidence for the use of cannabinoid-based therapies for the management of ErbB2-positive breast cancer." (PMID 20649976, 2010). "These Erbicin-derived immunoagents (EDIAs) target an ErbB2 epitope on breast cancer cells different from that of trastuzumab." (PMID 20051960, 2010). "Metastasis was also studied for multiple reasons; first, ErbB2 expression is well known to correlate with distant metastasis in human clinical breast cancer." (PMID 20825649, 2010). "On the basis of the ErbB2 assessment results from 14,398 patients in 7 Asian countries, our literature survey indicated that the reported prevalence of ErbB2-positive breast cancer has varied from 6% to 65%." (PMID 20715159, 2010). "Msi1 was expressed in 55% of the breast cancer cell lines and correlated with ErbB2 expression in 50% of the cell lines." (PMID 20727204, 2010). "Nevertheless, we also examined three more breast cancer cell lines, ErbB2-overexpressing BT474 and ErbB2-low-expressing MDA-231 and MCF-7, in order to confirm our findings from MDA-MB-435 cells." (PMID 20144215, 2010). "We identified AS transcripts that were differently modulated by ERBB2-mediated expression and that can be tested as molecular markers for breast cancer." (PMID 21210970, 2010). "When the results obtained using any of the assessment methods were examined, the prevalence of ErbB2-positive breast cancer varied widely (range, 6%-65%)." (PMID 20715159, 2010). "Although preliminary, our data suggested an inverse correlation between ErbB2 and ISG expression, supporting a role for repressed basal ISG expression in the pathogenesis of ErbB2-dependent breast cancer." (PMID 20840765, 2010). "The EGFR and ERBB3 are overexpressed in 50–70% of lung, colon and breast carcinoma; ERBB2 is overexpressed in 30% of breast cancer patients; ERBB4 is expressed in 50% of breast cancer patients and 22% of colon cancer patients." (PMID 20010942, 2010). "Abnormal high levels of ERBB2 are present in approximately 18–20% of breast cancers and gene amplification is the predominant mechanism leading to ERBB2 overexpression which in turn enhance cell proliferation (and references therein)." (PMID 20126619, 2010).
breast cancer (continued). "We simultaneously interfered with all AP-2 isoforms expressed in ErbB-2-positive murine N202.1A breast cancer cells by conditionally over-expressing a dominant-negative AP-2 mutant." (PMID 20459791, 2010). "Several studies have shown that up to 25% of breast cancers overexpress a member of the HER/ErbB transmembrane receptor tyrosine kinase family, ErbB2, associated with poor prognosis and with a more aggressive clinical behaviour." (PMID 20051960, 2010). "Enhanced ErbB2 assessment methods would enable us to further refine our understanding of the prevalence of ErbB2-positive breast cancer in Asia." (PMID 20715159, 2010). "The cSrc/FAK pathway plays an important role in ErbB2-regulated migration/invasion of breast cancer cells." (PMID 21034468, 2010). "Recently, 2 large studies of breast cancer registry data in the United States reported that women of Asian descent were more likely to have ErbB2-positive tumors than Caucasian women, suggesting possible racial differences." (PMID 20715159, 2010). "Bone metastasis formed by ERBB2-overexpressing breast cancer cell, BT474, was significantly blocked with trastuzumab, presumably due to reduced MARK pathway activity in tumour cells." (PMID 20010942, 2010). "The prevalence of ErbB2-positive breast cancer in Asia was influenced by the testing method and grading criteria used." (PMID 20715159, 2010). "There is a growing body of evidence suggesting an interaction between the IGF-IR and ErbB2 in clinical breast cancer." (PMID 20825649, 2010). "We measured the expression of ErbB2 on breast cancer cell lines JIMT-1 and KPL-4, directly derived from patients with aggressive trastuzumab-resistant tumours, and on MDA-MB-361 cells that are sensitive to trastuzumab." (PMID 20051960, 2010). "Breast cancers are now categorized into many subtypes: normal breast like, luminal A, luminal B, ERBB2 + and basal like." (PMID 21206711, 2010). "We focused on chromosome 17 because many regions of that chromosome are actively involved in recurrent amplifications during breast cancer development (including the ERBB2 amplicon)." (PMID 20158880, 2010). "Worldwide standardization of ErbB2 assessment is an important goal not only for obtaining unbiased data on the prevalence of ErbB2-positive breast cancer but also to ensure that patients receive the most appropriate treatment." (PMID 20715159, 2010). "The expression of hTid and ErbB-2 is inversely correlated in primary breast cancer (A) and in non mammary tumors (B)." (PMID 20565727, 2010). "With this in mind, Ming Tan and coworkers designed a novel CPP-based CPP specific for ErbB2-overexpressing breast cancer cells." (PMID 27713313, 2010). "We examined the effect of C3G on ethanol-mediated migration/invasion of breast cancer cells expressing high levels of ErbB2." (PMID 21034468, 2010). "The combination of lapatinib and trastuzumab has been shown to have a synergistic, antiproliferative effect against ErbB2-positive breast cancer cells in vitro." (PMID 20604919, 2010). "ErbB2 is overexpressed in 25-30% of human breast cancer cases and is correlated with poor prognosis and shorter disease free survival." (PMID 20825649, 2010). "It has been shown that FAK is essential for ErbB2/ErbB3-induced oncogenesis and breast cancer invasion." (PMID 21034468, 2010). "It marker to evaluate cell proliferation and prognosis when combined with other breast cancer markers, such as estrogen receptor, progesterone receptor and ERBB2." (PMID 20158880, 2010). "ERBB2 status was only determined for 47 of the study participants as routine testing for new breast cancer presentations was introduced only in late 2005, after the date of presentation for most of our patients." (PMID 20179710, 2010). "LUMB breast cancers are characterized by expression of HR along with HER2 associated genes (i.e., ERBB2 and GRB7) and a cell proliferation pattern designated by expression of MK167, CCNBI and MYBL2." (PMID 20492711, 2010).
breast cancer (continued). "This study demonstrated that the antimigratory or promigratory effects of Sema4D in breast cancer cell lines depend on the stoichiometry of the expression of Plexin-B1, Met and ErbB-2." (PMID 20858260, 2010). "We took as «baits» five bimodal genes reported as important breast cancer genetic markers - ERBB2, ESR1, PLAUR, FN1, and STAT1, and calculated the "close neighbor" gene groups that were synchronously expressed with each of them in the Sorlie295 set." (PMID 20158879, 2010). "This concurs with the observation that PSMB3 was co-expressed with ERBB2 in 34 breast cancer biopsies and also mapped within the same chromosomal location as the ERBB2 gene that is frequently amplified." (PMID 20543960, 2010). "Two such proteins with validated roles in breast cancer are ErbB2 (also known as Her2/neu), a member of the epidermal growth factor receptor family, and the type I insulin-like growth factor receptor (IGF-IR)." (PMID 20825649, 2010). "The following results were derived from a project aiming at the conditional expression of erbB2 in breast cancer cell lines." (PMID 21106052, 2010). "C3G attenuated ethanol-induced migration/invasion of breast cancer cells expressing high levels of ErbB2 (BT474, MDA-MB231 and MCF7ErbB2) in a concentration dependent manner." (PMID 21034468, 2010). "In particular, the frequency of amplification for clones on 17q12-q21, encompassing many genes including ERBB2/HER2 that is the most frequent amplified gene in breast cancers, was higher in the cell lines than in tissue specimens." (PMID 20070913, 2010). "ErbB2 is overexpressed in 25-30% of all breast cancers due to gene amplification, and is correlated with disease progression, advanced tumour stage, decreased survival, poor response to therapy and metastasis." (PMID 20840765, 2010). "Third, in a large-scale RNA interference screen, PTEN silencing conferred resistance to trastuzumab in breast cancer cells with ERBB2 amplification." (PMID 20712882, 2010). "ErbB2-positive breast cancer is characterized by highly aggressive phenotypes and reduced responsiveness to standard therapies." (PMID 20649976, 2010). "Further evaluation of human breast cancer tissues determined that MET overexpression was highly correlated with ER–/ERBB2– and basal-like breast cancers." (PMID 21049054, 2010). "For the validation study, pyrosequencing assays for 19 CpG loci were conducted in an independent cohort of 187 normal/breast cancer paired samples encompassing 47 basal-like, 44 ERBB2+, 48 luminal A, and 48 luminal B samples." (PMID 20920229, 2010). "The results showed a similar distribution (accuracy = 98%) and confirmed that ER+ and ER- ERBB2-amplified breast cancers are different (Fisher exact's test, p = 0.019; O.R. = 4.39)." (PMID 20932292, 2010). "Given the increasing incidence of breast cancer in Asia and the clinical consequences of ErbB2-positive breast cancer, insight into the prevalence of ErbB2-positive tumors in Asia is important." (PMID 20715159, 2010). "Ethanol increases the phosphorylation of ErbB2 and enhances the adhesion of breast cancer cells with high levels of ErbB2 to the ECM as well as the assembly of focal adhesions in these cells." (PMID 21034468, 2010). "Here we show that hypermethylation of the DMR2 of IGF2 is specifically observed in ERBB2 positive breast cancers providing a new potential mechanistic link between IGF1R expression and ERBB2 status via IGF2 methylation status." (PMID 20338046, 2010). "The ErbB2 gene is a member of the epidermal growth factor receptor family and is overexpressed in about 30% of breast cancer." (PMID 27713313, 2010). "A statistically significant inverse correlation between htid and ErbB-2 expression was found in human breast (p < 0,0001) and non-mammary tumors (p < 0,007), and in transgenic mice carrying the rat HER-2/neu oncogene." (PMID 20565727, 2010). "Herceptin (trastuzumab) is used in patients with breast cancer who have HER2 (ErbB2)–positive tumours." (PMID 21203579, 2010).
breast cancer (continued). "It is well understood that breast cancer tissue and cell lines can contain upwards of 50-100-fold higher levels of ErbB2 protein compared to normal tissue and these levels are typically associated with gene amplification and poor prognosis." (PMID 20825649, 2010). "The ERBB2 locus has been extensively studied and has been proposed to be one of the most important loci in breast cancer." (PMID 20158880, 2010). "Trastuzumab development has led to a significant improvement in the outcomes of patients with ErbB2-positive breast cancer." (PMID 20051960, 2010). "Taken together, our results in Cowden disease and multiple results in the literature strongly support a central role for the ERBB2-PTEN-PIK3CA-AKT pathway in the biology of breast cancer." (PMID 20712882, 2010). "In the original microarray-based classification of breast cancer, Perou and colleagues identified a group of tumors enriched in ERBB2-amplified tumors that they called the HER2 class." (PMID 20712882, 2010). "Given the prominent role of ErbB2 in breast cancer and the previously discussed interactions with the IGF-IR, this oncogene was an attractive candidate." (PMID 20825649, 2010). "On the other hand, expression of estrogen and/or progesterone receptors is a typical feature of luminal A and B subtypes, whereas the ERBB2 and basal-like subtypes of breast cancer rarely express hormone receptors." (PMID 20716336, 2010). "Gene amplification and overexpression of ERBB2 has been reported in several types of cancer, including the breast cancer, and has been shown to contribute to a poor clinical outcome." (PMID 20859285, 2010). "We have previously demonstrated that ethanol increased the migration/invasion of breast cancer cells expressing high levels of ErbB2." (PMID 21034468, 2010). "Contrarily, 14-3-3ζ cooperates with ErbB2 to promote EMT and progression of ductal breast carcinomas to invasive cancer, and its overexpression associates with breast cancer recurrence." (PMID 20421926, 2010). "The high cardiotoxic effects of trastuzumab, an anti-erbB2 humanized monoclonal antibody, which has been observed in erbB2+ breast cancer patients that have been pre-treated or co-treated with anthracyclines, depend on the loss of this survival pathway." (PMID 21187925, 2010). "We produced correlation tables that included both the genes of the TNFAIP1/POLDIP2 SFGM and the ERBB2 CR and their neighboring genes in the Uppsala and Stockholm breast cancer cohorts." (PMID 20158880, 2010). "For example, analysis of EPHA2 knockout mice revealed that EPHA2 enhances ErbB2-mediated tumorigenesis in MMTV-Neu mammary tumor mouse models." (PMID 20979646, 2010). "Nordihydroguaiaretic acid (NDGA), a dual inhibitor of IGF-IR and ErbB2, was shown to promote cell death in trastuzumab resistant human breast cancer cell lines." (PMID 20825649, 2010). "It is widely accepted, that the most common mechanism for ERBB2 activation in breast cancer is gene amplification." (PMID 20158880, 2010). "ErbB3 is often overexpressed in human breast cancers, frequently in conjunction with overexpression of the proto-oncogene ErbB2/HER2." (PMID 20492690, 2010). "Eleven of 20 human breast cancer cell lines (55%) expressed Msi1, and 13 cell lines showed a strong correlation between Msi1 and ErbB2 (P = 0.02)." (PMID 20727204, 2010). "Overall and relapse-free survivals were most favourable for luminal A tumours and least favourable for ERBB2+ and basal-like breast cancers." (PMID 20520800, 2010).